CD70 (CD70 molecule)
Diseases named in the same sentence as CD70 in open-access papers (continued):
Sharing a sentence is not in itself a finding about the gene and the disease.
cancer (continued). "CD70, as a pan‐cancer target abnormally overexpressed across various hematologic and solid tumours while maintaining highly restricted expression in normal tissues, demonstrates significant clinical potential in diagnosis, treatment, and prognostic assessment." (PMID 40629902, 2025). "This review critically assesses CD70’s role in cancer immunotherapy by analyzing its mechanistic contributions to tumorigenesis and surveying current targeting strategies." (PMID 40896423, 2025). "This outcome highlights the potential of CD70-targeted CAR-T therapy as an effective treatment option for cancers expressing CD70, offering hope for durable responses in certain patient populations." (PMID 40312353, 2025). "We noticed a widespread dysregulation of RNA modification enzymes across multiple cancer types, focusing on the regulation of the immune checkpoints CD70, CD80, and TIGIT." (PMID 40565233, 2025). "Solid tumors link CD70 to cancer stem cells and EMT through EMT gene induction and MAPK/RhoE activation." (PMID 40896423, 2025). "In our evaluation of CD70 as a potential cell surface target for RCC immunotherapy, we conducted an analysis of CD70 mRNA expression across the TCGA database by pan-cancer view." (PMID 38637886, 2024). "In this study, we analyzed CD70 expression in various cancers, including DLBCL, using TIMER, GEPIA, GENT2, TNMPlot, GSCA, and GEO online databases." (PMID 39446784, 2024). "In contrast to its restricted expression in normal tissues, CD70 is aberrantly expressed in cancer: in oncology, CD70 is often overexpressed in malignant cells, either independently (solid tumors) or along with CD27 (hematological malignancies)." (PMID 38638433, 2024). "Collectively, our data underscores the preclinical efficacy and safety of SAP UCAR-T cells targeting CD70, paving the way for a promising therapeutic strategy against CD70-positive cancers." (PMID 39906740, 2024). "Our results indicate that CD70 is an attractive therapeutic target expressed on both cancer cells and CAFs in CRC and PDAC patients." (PMID 38331849, 2024). "Overexpression of CD70 has been observed in various hematologic and solid malignancies, playing a crucial role in cancer pathophysiology." (PMID 39446784, 2024). "Collectively, these results highlight the altered expression of CD70 in human cancers compared to normal tissues, with CD70 being overexpressed in most cancers, particularly in DLBCL." (PMID 39446784, 2024). "We first analyzed CD70 expression across various cancers, including DLBCL, using multiple online databases (TIMER, GEPIA, GENT2, TNMPlot, GSCA, and GEO)." (PMID 39446784, 2024). "The analysis of 533 KIRC samples revealed that the higher CD70 expression always related higher grade and late cancer stage." (PMID 38637886, 2024). "Additional analyses using the TNMplot and GSCA databases further corroborated these findings, demonstrating significant differences in CD70 expression between human cancers and adjacent normal tissues." (PMID 39446784, 2024). "Accumulating evidence has demonstrated the prognostic and therapeutic value of CD70 in malignant tumors, including acute myeloid leukemia and T-cell lymphomas." (PMID 39446784, 2024). "In a pan-cancer analysis, CD70/CD27 signaling was, surprisingly, found to contribute to immune evasion, potentially through CD70-mediated Treg recruitment." (PMID 37345056, 2023). "CD70 has different roles in predicting the prognosis of different cancers, and participate cancer progression through immunotherapy." (PMID 37100777, 2023). "CD70 was found to be upregulated across many cancers, while CD70/CD27 expression correlated with Treg infiltration levels." (PMID 37345056, 2023). "CD70 is a member of the tumor necrosis factor (TNF) superfamily and has recently been considered as a potential target for AML; the normal expression of CD70 is restricted to activated immune cells, but its expression is increased in many cancer types." (PMID 36835136, 2023).
cancer (continued). "A phase I/II clinical trial evaluating the safety and efficacy of CD70 CAR NK cells for cancer immunotherapy is underway (NCT05092451)." (PMID 37475035, 2023). "Cluster of differentiation 27 (CD27) plays an important role in T-cell activation; due to binding with its natural ligand CD70, T-cell proliferation and differentiation to effector and memory T-cells is enhanced, making it a potential target in cancer therapy." (PMID 36157879, 2022). "Targeting/blocking CD70/CD27 signalling thus represents an attractive therapeutic strategy for multiple types of cancers." (PMID 36471481, 2022). "CD70 has recently been proposed as an emerging target for cancer immunotherapy, particularly in the case of RCC where its overexpression in ccRCC is thought to be driven by stabilization of hypoxia inducible factors." (PMID 35837094, 2022). "Our data show that nanobodies Nb-2B3 and Nb-3B6 are potential attractive theranostic agents for CD70-expressing cancers." (PMID 36239354, 2022). "In hematological malignancies, cancer cells co-express CD70 and CD27 promoting stemness, proliferation and survival of malignancy." (PMID 34991665, 2022). "Bound to its ligand CD70, CD27–CD70 interactions play an important role in enhancing T‐cell proliferation and differentiation and therefore is a potential target in cancer immunotherapy." (PMID 35029050, 2022). "Further studies on the acetylation/deacetylation of CD70 in various tumors will be beneficial in establishing a solid theoretical foundation for cancer immunotherapy." (PMID 35585975, 2022). "At present, there is no report about CD70 nanobodies, and the nanobodies identified in our study have the potential as attractive theranostic agents for CD70-expressing cancers." (PMID 36239354, 2022). "As such, numerous promising therapeutic approaches targeting CD70 have been under investigation, both in preclinical and clinical settings with the aim of improving treatment outcomes of cancer patients." (PMID 34991665, 2022). "Combination regimens with CD70 targeting agents have already been explored in clinical setting for certain cancer types." (PMID 34991665, 2022). "Compared with the naïve spleen and spleens of cancer‐bearing mice, CD70 was unchanged in cancer nodules." (PMID 34570961, 2021). "The CD27/CD70 axis can be targeted with antibodies and its blockade has potential for cancer immunotherapy." (PMID 34430923, 2021). "Most of the solid tumors lack CD70 expression, whereas only hematologic cancers have a high frequency of CD70+ cancer cells." (PMID 34568077, 2021). "CD27 and its ligand CD70 are involved in the regulation of cellular immune responses to cancer and also enhance T cell proliferation and memory-cell formation." (PMID 33164640, 2020). "We next determined CD70 protein expression and how this correlates with the efficiency of anchorage-independent growth in human cancer cell lines." (PMID 29721188, 2018). "In conclusion, we have identified a regulatory mechanism by which the oncogenic driver HIF-2α up-regulates CD70, a cell surface protein that is reflective of aggressive cancer cells." (PMID 29721188, 2018). "To validate the importance of CD70 in increased anchorage-independent growth of cancer cells, we next carried out siRNA knockdown of CD70 expression." (PMID 29721188, 2018). "Along with the patient data showing that high expression of these factors is correlated with poor patient prognosis, these results suggest that CD70 or HIF-2α can be promising targets for cancer therapeutics." (PMID 29721188, 2018). "Due to the prominent role of CD70 in cancer, the applications for CD70 targeted therapy have also been developed." (PMID 29721188, 2018). "Taken together, these data demonstrated a regulatory link between HIF-2α function and CD70 expression, which promotes cancer cell proliferation." (PMID 29721188, 2018).
cancer (continued). "Taken together, these studies indicate that chronic hypoxic conditions allow CD70+ cells to emerge from CD70– populations and this is likely mediated by epigenetic modifications in cancer cells." (PMID 29721188, 2018). "Inspection of the analyzed gene set revealed that, among the ten most specific immune response cancer genes, five were bound to or an integral part of the plasma membrane (CD70, HLA-B, TNF, TNFRSF14, and CD79B)." (PMID 26856619, 2016). "In spite of the ambiguous role of CD70 in cancer development and progression, its substantial expression in certain cancers would make CD70 an attractive immunotherapeutic target." (PMID 25792975, 2015). "CD70 is highly expressed on various types of cancers and as such is a bona fide target for antiCD70 antibody mediated therapy." (PMID 23840967, 2013). "Earlier studies on the expression of CD70 in cancers have relied on flow cytometric analysis for haematologic malignancies and IHC on limited frozen tissues for carcinomas." (PMID 20664585, 2010). "In this study, we expanded our analysis of CD70 expression in various types of carcinomas to identify new potential indications for SGN-75." (PMID 20664585, 2010). "Immunohistochemical analysis of CD70 expression in multiple carcinoma types demonstrated strong CD70 staining in RCC tissues." (PMID 16892042, 2006). "CD70, which is a ligand belonging to tumour necrosis factors, exhibits aberrant overexpression among multiple hematologic and solid malignancies and has drawn extensive research enthusiasm as a target to treat and diagnose cancers." (PMID 40629902, 2025). "CD70 is aberrantly overexpressed in multiple hematologic and solid tumours while exhibiting minimal expression in normal tissues, making it an attractive target for integrated cancer diagnosis and therapy." (PMID 40629902, 2025). "A deeper understanding of CD70 biology may catalyze the development of precision immunotherapies to improve cancer outcomes." (PMID 40896423, 2025). "CTX110 (NCT04035434), targeting CD19+ cancers (B cell leukemias and lymphomas), and CTX130 (NCT04502446 and NCT04438083), targeting CD70+ cancers (T cell lymphomas and renal cell carcinomas), both knockout the β2M gene, a subunit of the major histocompatibility complex class 1 (MHC-I) subunit." (PMID 41476860, 2025). "Additionally, unmodified T cells (mock T) displayed negligible cytotoxicity against cancer cells, further confirming the specificity of the anti-CD70 CAR-T cells." (PMID 40165944, 2025). "Also, when compared to corresponding adjacent healthy tissues, considerable variability was observed in CD70 expression among 22 individual cancer cases." (PMID 40675157, 2025). "CD70 has been found to correlate with immune checkpoint gene expression across various cancers." (PMID 40629902, 2025). "Our findings suggest that m6A readers might selectively regulate immune checkpoint expression, affecting CD70/CD80 dynamics in various cancer types." (PMID 40565233, 2025). "This elevated expression positions CD70 as a promising target for anti-cancer immunotherapy." (PMID 39906740, 2024). "Exploiting CD70 as anti-cancer target has already shown promising results in clinical trials." (PMID 38331849, 2024). "Notably, in NSCLC tumors that develop EGFR-TKI refractory disease, CD70 is upregulated by refractory cancer cells." (PMID 37545491, 2023). "[68Ga]Ga-NOTA-anti-CD70 VHH showed excellent in vivo targeting of CD70 in human cancer xenografts." (PMID 37093350, 2023). "The high renal uptake may hamper the low-level background activity required to detect low levels of CD70 expression expected in some cancer patients." (PMID 37093350, 2023). "CD27 is a member of the tumor necrosis factor receptor superfamily and, in combination with its natural ligand CD70, activates the differentiation of T cells into effector and memory T cells and thus has potential as an immunomodulatory target in cancer therapy." (PMID 36686701, 2022).
cancer (continued). "However, the tumourigenic role of CD70 in cancer, especially in lymphoid malignancies, remains elusive." (PMID 36471481, 2022). "Consequently, therapies targeting CD70 hold great potential to combat both early and advanced stages of cancer." (PMID 34991665, 2022). "CD70 belongs to the tumor necrosis factor (TNF) family which is critical in cancer immunotherapy." (PMID 36497225, 2022). "Therefore, CD70-TTCs have the potential to both eliminate cancer cells and modulate immune responses." (PMID 36726355, 2022). "To check whether the cancer microenvironment harbored factors that could influence Th17 subpopulations, we evaluated the mRNA levels of CD70 (the CD27 ligand), IL‐6, and TGF‐β1 in the lysates of cancer nodules and spleens." (PMID 34570961, 2021). "RP11‐89 was significantly correlated with the expression of CD44, CD70 and LAGLS9 in pan‐cancers and was significantly associated with the abundance of activated CD4 T cells, activated CD8 T cells and effector memory CD4 T cells in pan‐cancers." (PMID 33797188, 2021). "CD70 constitutive expression has been reported in the field of cancer." (PMID 34267616, 2021). "Important genes that impact cancer, such as CD70, JAK3 and GDF15, are found on ch19." (PMID 34063545, 2021). "In addition, a trial is testing the safety and activity of administering peripheral blood lymphocytes transduced with a CD70-binding Chimeric Antigen Receptor (CAR) to patients with CD70-expressing cancers." (PMID 31060337, 2019). "Therefore CD70 is also a marker of cancer aggressiveness, and growth advantage in diverse cancer types." (PMID 29721188, 2018). "Here, we report an involvement of the microenvironmental parameter hypoxia and the hypoxia-regulated HIF-2α transcription factor in the epigenetic regulation of CD70 expression, which may contribute to enhanced anchorage-independent growth of cancer cells." (PMID 29721188, 2018). "Importantly, both HIF-2α and CD70 expressions were correlated with poor prognosis of cancer patients." (PMID 29721188, 2018). "CD70 expression has been increasingly linked to carcinomas or solid tumors while it is not expressed in intact non-lymphoid cells." (PMID 29721188, 2018). "In addition, CD70 on cancer cells is an attractive candidate for targeted immunotherapy due to its restricted expression on non-malignant cells." (PMID 25792975, 2015). "This raises the question whether CD70 exerts a biological function in certain cancer types or certain cancer cells." (PMID 25792975, 2015). "Finally, we have shown in vitro that ARGX-110, a CD70-specific mAb with enhanced ADCC effects, is able to successfully mediate lysis of CD70+ cancer cells." (PMID 25951351, 2015). "Further preclinical studies are needed to evaluate whether this dualistic and context-dependent use of CD70/CD27 for cancer therapy is feasible." (PMID 23840967, 2013). "This expression pattern establishes CD70 as a potential target for antibody-based cancer therapy." (PMID 23840967, 2013). "However, caution is required in terms of exploiting the immunoregulatory role of CD70/CD27 for cancer immunotherapy." (PMID 23840967, 2013). "All these observations suggest that the direct induction of TIC apoptosis by persistent expression of FasL, RCAS1 or perhaps other apoptosis-inducing ligands (e.g. CD70) on carcinoma cells plays a role in the ability of carcinoma cells to escape from the anti-carcinoma immunity." (PMID 21255410, 2011). "However, it is worth noting that clinical studies on a variety of additional possible antigens may be conducted in the future (cancer testis antigens, CD70, CD126, CD229)." (PMID 35672793, 2022). "Importantly, although the CD27-CD70 axis is known for its immune stimulatory effects, CD70-expressing (pancreatic) cancer cells may also instigate immune tolerance by increasing the frequency of activated Tregs." (PMID 34439292, 2021).
cancer (continued). "Therefore, targeting the CD70/CD27 axis could be of great relevance in treating cancer types that currently lack effective treatment strategies." (PMID 31652572, 2019). "Our findings support a model in which RNA modifications, particularly m6A, act as fine-tuners of CD70, CD80, and TIGIT expression across multiple cancer types." (PMID 40565233, 2025). "Increasing evidence supports its function as a modulator of key immune regulatory molecules, including CD70, CD80, and TIGIT, influencing cancer immune evasion." (PMID 40565233, 2025). "In KIRC, the CD70 and EDN pathway networks were more prominent in low-PIMS cancer cells, while the MK and VEGF pathways were more active in high-PIMS cancer cells in PRAD." (PMID 40221501, 2025). "In contrast, in SCLC, that was lately described as a cancer with a predominantly macrophage-rich TME, CD70 expression has a strong representation from CD68 + TAMs, and the molecule’s coexpression on T- or B-cells is not prevalent." (PMID 40205178, 2025). "CD70 has been postulated as a putative pan-cancer target for immunotherapy, which is supported by bulk RNA-seq data from the TCGA PCAWG Firehose cohort demonstrating varying CD70 mRNA expression levels across 28 different cancer types." (PMID 38331849, 2024). "The major signalling pathways specific to the cancer condition are VEGI, APRIL, IL10, and CD70, and these pathways mostly involve the signalling from immune cells." (PMID 39149248, 2024). "Meanwhile, studies of the tumor microenvironment using markers specific to immune cells revealed that various cancers can express a series of CD markers: CD36, CD58, CD70, CD160, CD276, CD320, and CD336." (PMID 36754910, 2023). "Learning from the trials of the immune checkpoint inhibitor therapies, it is possible to design novel approaches targeting the IGM-type of cancer plasticity: early clinical examples are CD20, CD27/CD70, CD166, and IDO." (PMID 36754910, 2023). "We hypothesized that the anti-CD70 VHH recognizes a distinct epitope on the CD70 antigen that is different from the one recognized by the mouse anti-human CD70 antibody, which represents a potential advantage for detection of this target in cancer patients treated with CD70-targeting therapies." (PMID 37093350, 2023). "Other antibodies targeting stimulatory or inhibitory coreceptors, including OX40, LAG-3, CD70, and GITR, are being tested in cancer studies as Afuc forms to enhance antibody immunomodulatory functions in vivo." (PMID 35775486, 2022). "CD70 had been proven to play a role in TME through its effect on human T cells and has become an emerging target for cancer immunotherapy." (PMID 35568859, 2022). "Knockouts of some “cancer drivers” of DLBCL, including BCL2, BCL6, NFKBIA and CD70, showed only modest promotional effects on cell proliferation." (PMID 33911074, 2021). "There are several other examples for the ectopic expression of immune cell genes in cancer, such as CD36, CD70, CD40, CD47, CD172 and IDO1." (PMID 34885093, 2021). "In cancer vaccine therapy, blocking CD70 markedly reduced the effect of CD4+ T cell-mediated aid, such that CD70 blockade almost completely abolished the therapeutic effect of the “Help” vaccine." (PMID 33737923, 2020). "We have identified a role for HIF-2α in the hypoxic regulation of the cancer marker CD70 that occurs through DNA methylation mediated by DNMT1 and drives cancer cell proliferation." (PMID 29721188, 2018). "In the section next I will discuss the biology of CD40L/CD40, CD70/CD27, 4-1BBL/4-1BB and OX40L/OX40 and highlight their current status for cancer immunotherapy." (PMID 23840967, 2013). "Various co-stimulatory TNFL/TNFR pairs, including CD40L/CD40, CD70/CD27, 4-1BBL/4-1BB, and OX40L/OX40, have gained prominence as possible targets for cancer immunotherapy, in particular with the aim of induction or (re)activation of antitumor T-cell immunity." (PMID 23840967, 2013).